CCNA2 (cyclin A2)
Diseases named in the same sentence as CCNA2 in open-access papers (continued):
Sharing a sentence is not in itself a finding about the gene and the disease.
cancer (continued). "Other mechanisms include silencing of cyclin A2 (CCNA2) and inhibition of cancer cell migration." (PMID 37143325, 2023). "The results indicated that CCNA2, CCNB1, CDK1 and CDKN2A were expressed in cancer epithelial cells." (PMID 37265472, 2023). "The CCNA2 expression is positively correlated with Th2 cell infiltration and negatively correlated with CD4+ central memory and effector memory T-cell infiltration in different cancer types." (PMID 35480884, 2022). "Similarly to CCNA2, overexpression of CCNB1 and CDK1 has been detected in several human cancers, including PDAC." (PMID 36359879, 2022). "Considering with complex and heterogeneity of TME and lack of robust immune biomarkers in KICH, KIRC, and THCA, CCNA2 seemed to be new indicator for those cancers." (PMID 35401923, 2022). "The current study also found that CCNA2 expression was positively correlated with DNA methylation and MMR in most cancers, which suggested that CCNA2 might influence DNA methylation level or MMR state, thus determining the clinical outcomes of cancer patients." (PMID 35401923, 2022). "Moreover, Comp1 and Comp2 significantly blocked the interaction between CCNA2 and CDK2, leading to irreversible arrest of the cell cycle of cancer cells." (PMID 36325324, 2022). "Although accumulating evidence has verified the relationship between CCNA2 and cancers, no pan-cancer analysis about the function and the upstream molecular mechanism of CCNA2 is available." (PMID 35480884, 2022). "Involved genes (CCNA2, MKI67, and KIF11) were found with abundant expression levels in many tissues, and they showed a significantly upregulated expression pattern in many cancer types." (PMID 35186743, 2022). "Taken together, these results suggested that β-carboline-3-carboxylic acid dimers could arrest the cell cycle by suppressing TK1, DBF4, CCNA2, CDK2, and PLK1, together with influencing some cancer-related pathways to inhibit MG-63." (PMID 36325324, 2022). "Consistent with the gene expression in this study, and protein levels within a previous study, 3D cultured cells had upregulated protein levels of markers for cancer stemness (CD44) and pluripotency (POU5F1), and downregulated levels of markers for proliferation (CCNA2) and differentiation (ERS1)." (PMID 34869246, 2021). "In the end, the molecular function of Cdc20 in pan-cancer analysis indicated that BUB1, CCNA2, CCNB1, CDK1, MAD2L1, and PLK1 might play a critical role in its oncogenic function." (PMID 34527589, 2021). "Studies have shown that CCNA2, HAS2 and TIMP1 can regulate the cell cycle of cancer cells." (PMID 33619234, 2021). "3D cultured cells were also shown to have lower levels of genes related to cell proliferation or mitosis (CCNA2, MKI67, and BUB1) and differentiation (ESR1) relative 2D cultured, consistent with higher levels of a cell cycle inhibitor (CDKN1) and cancer stemness–related markers (CD44 and MALAT1)." (PMID 34869246, 2021). "Furthermore, AREG affected downstream molecules like BIRC5, CCNA2, CCNB2, TOP2A, MMP9, MMP1, CXCR4, have roles in development and progression of various types of cancers." (PMID 30517191, 2018). "Several synthetic lethality screens have been performed on KRAS mutant cancer cell lines to determine potential targets, and results have frequently included genes important in cell cycle progression or mitosis, such as CDK1, cyclin A2, PLK1, and CDC6." (PMID 27167191, 2016). "In this study, we have developed a cyclin A2-luciferase (CYCA-Luc) fusion protein targeted for ubiquitin-proteasome dependent degradation, and have evaluated its utility in screening S-phase targeted anti-cancer drugs." (PMID 23301056, 2013). "In addition, CCNA2 could positively regulate TAP1, TAP2, CD276, MICB, PVR, and ULBP1 in almost all the cancer types." (PMID 35401923, 2022). "However, there is still no pancancer level analysis of the role of CCNA2 in various cancers, and the exact role of CCNA2 in tumorigenesis remains incompletely understood." (PMID 35401923, 2022).
cancer (continued). "Moreover, the pan-cancer analysis of the molecular function of Cdc20 indicated that BUB1, CCNA2, CCNB1, CDK1, MAD2L1, and PLK1 might play a critical role in interaction with Cdc20." (PMID 34527589, 2021). "The enrichment of cancer cells with pluripotency features after treatments with 4OHT and fulvestrant in PDS cultures as depicted by gene expression analysis, was further supported by an increase in Sox2 protein levels, and a reduction in PgR and Ccna2 proteins levels." (PMID 34172801, 2021). "Cyclin A2, whose expression is frequently altered in diverse human cancers, was first identified over 30 years ago; however, to-date, not much has been done to potentially exploit it for cancer therapeutics." (PMID 29207607, 2017). "Therefore, inhibitors of CDK2 may not be appropriate for cancer therapy and more efforts are focused on inhibition of cyclin A2 and/or cyclin A2- CDK2 complex activity." (PMID 19684852, 2009). "However, there is a significant positive correlation between CCNA2 and Th2 cells and significant negative correlations between CCNA2 and CD4+ central memory and effector memory T cells by the xCell estimation algorithm in almost all cancer types." (PMID 35480884, 2022).
infection (32 papers, 2005 to 2026). The state of being infected such as from the introduction of a foreign agent such as serum, vaccine, antigenic substance or organism. "In this study we aimed to deepen our understanding of HCMV-Cyclin A2 interaction by investigating the cause and consequences of Cyclin A2 repression during lytic infection." (PMID 25393019, 2014). "CCNA2 ablation was accomplished by infection with adenovirus encoding cre-recombinase." (PMID 27425845, 2016). "In fact, repression of the Cyclin A2 promoter in the early phase of infection might account for the only moderate effect of pUL21a-RXL mutation on Cyclin A2 protein expression at 24 hpi." (PMID 25393019, 2014). "The cultured adult human cardiomyocytes were transduced with cTnT-hCCNA2 (test) versus cTnT-eGFP (control) adenoviruses with a multiplicity of infection (MOI) of 100 each for assessing the induced expression of CCNA2." (PMID 40470201, 2025). "This is exemplified by the expression pattern of the proliferation markers Ki67 (Mki67), Pcna, Ccna2 and the minichromosome maintenance complex genes Mcm2 and Mcm6, which peak late in infection (Cell Cycle panel)." (PMID 38107402, 2023). "In contrast, Cyclin A2 and B1 induction was much weaker after infection with the M117-ΔCter2, M117-ΔNter or the ΔM117 mutants." (PMID 30532172, 2018). "The tegument protein pp150 senses the cellular cyclin A status at the beginning of infection and restricts the onset of IE gene expression to the G0/G1 phase, where cyclin A2-CDK is inactive." (PMID 28129404, 2017). "We next asked what impact, if any, the increased amounts of Cyclin A2 and B1 at early-late times of infection have on viral replication." (PMID 25393019, 2014). "It remains to be determined how distinct HCMV genotypes and varying infection conditions influence the actual outcome of pUL21a-Cyclin A2 interaction on IE2 expression and virus growth." (PMID 25393019, 2014). "Recently, we discovered that HCMV employs an RXL/Cy motif in the pp150 tegument protein to sense the cellular Cyclin A2 status right at the beginning of an infection." (PMID 25393019, 2014). "RT-PCR analysis performed 24 hours post infection with an adenovirus vector expressing DN-NF-YA (Ad-DN-NF-YA) shows that cyclin A2, B2, cdk1, cdc25C, topoisomerase IIα mRNAs were greatly down-regulated (lane 3)." (PMID 18431504, 2008). "Cyclin A2 and B1 protein levels were upregulated upon infection with MCMV-M117-FL or MCMV-M117-M4." (PMID 30532172, 2018). "CDK2 and CCNA2 play vital roles in regulating the eukaryotic cell division cycle, but IAV tries to arrest the cell cycle during infection." (PMID 35019712, 2022). "In cultured VSMCs, treatment with PGE1-OH or infection of Ad-EP4 also significantly upregulated the mRNA levels of genes related to cell proliferation including Ki67, Foxm1, Ccna2, Ccnb1, Ccnd1, Ccnd2, Ccne1, and CDK2." (PMID 36078128, 2022). "To investigate whether YAP6SA stimulates CM division, we collected postnatal mouse hearts after 3 d of AAV9 infection and performed immunofluorescence (IF) to examine the CM cell cycle activity using the cell cycle markers CDK2, pHH3, and cyclin A2." (PMID 41577381, 2026). "In general agreement with our data, proteomic analysis indicated that cyclin A2, B1, B2, H, and CDKs 1, 2, 6, 7 levels were not altered by infection." (PMID 35216024, 2022). "Similarly to what was observed in mouse cells, infection with a WT MCMV induced the expression of the E2F target genes Cyclin E1 and PCNA, and to a lower extent of Cyclin A2." (PMID 30532172, 2018). "For example, CCNA2 and CDK1 are key regulators of cell cycle progression, and their repression may lead to cell cycle arrest, thereby reducing the proliferation of infected cells and limiting the spread of the infection." (PMID 41000417, 2025).
adenocarcinoma (4 papers, 2004 to 2022). A common cancer characterized by the presence of malignant glandular cells. "The expression levels of cyclin E correlated with those of cyclin A2 (Spearman’s rank correlation coefficient [rs] = 0.38, P < 0.0001) and p16 (rs = 0.32, P = 0.0003) in adenocarcinoma." (PMID 26681199, 2015).
colon (2 papers, 2021 to 2025). "Interestingly, the downregulated DEGs, such as MAD2L1, CCNA2, MCM2, MCM4, FEN1, and CDK6, were enriched in DNA replication, tyrosine metabolism, and cell cycle pathways, which are commonly upregulated in colon cancer." (PMID 34521988, 2021).
CCNA2 also shares sentences with these, for which no sentence is quoted: oral cancer (6 papers); atherosclerosis (4); triple-negative breast carcinoma (4); astrocytoma (3); cardiovascular disease (3); focal segmental glomerulosclerosis (3); head and neck cancer (3); medulloblastoma (3); sarcoma (3); soft tissue sarcoma (3); adrenocortical cancer (2); Alzheimer disease (2); B-cell lymphomas (2); carcinosarcoma (2); chronic hepatitis (2); cyst (2); dysplasia (2); immune system disorder (2); lymphoma (2); prostate adenocarcinoma (2); pulmonary fibrosis (2); renal cell carcinoma (2); retinoblastoma (2); small cell lung carcinoma (2); thymoma (2); uterine carcinosarcoma (2); vulvar carcinoma (2); Wilms tumor (2); achondroplasia (1); acute leukemia (1).
A further 83 diseases each share a sentence with CCNA2 in 1 paper.